IDH1 (isocitrate dehydrogenase (NADP(+)) 1)
Diseases named in the same sentence as IDH1 in open-access papers (continued):
Sharing a sentence is not in itself a finding about the gene and the disease.
astrocytomas (continued). "Furthermore, we observed that most recurrences had a consistent IDH1 and ATRX status with their matched primary tumors and demonstrated the progressive pattern of grade II astrocytoma/oligodendroglial tumors and anaplastic oligoastrocytoma with or without IDH1-R132H." (PMID 26918938, 2016). "In addition, we also observed that most recurrences had a consistent IDH1 and ATRX status with their matched primary tumors and demonstrated the progressive pattern of grade II astrocytoma/oligodendroglial tumors and anaplastic oligoastrocytoma with or without IDH1-R132H." (PMID 26918938, 2016). "A majority of oligoastrocytomas (63.8%) exhibited the IDH mutation in the absence of TERT promoter mutations, much like Grade II-III astrocytomas; however, a fraction (22.4%) of oligoastrocytomas presented with both TERT promoter and IDH1/2 mutations, similar to oligodendrogliomas." (PMID 24722048, 2014). "In terms of diagnosis, IDH1/2 genotyping is helpful in predicting the histological grade (2016 classification) and is now systematically used to make the distinction between GBM and non-GBM tumors (IDH-mutated grade 4 astrocytomas) in the recent classification." (PMID 36400876, 2022). "Moreover, patients with high FilGAP score and IDH1 mutant‐type astrocytomas had significantly the best Overall survival (OS) and Progression‐free survival (PFS), in contrast to the patients with low FilGAP score and wild‐type IDH1 tumors who had the worst prognosis." (PMID 27790861, 2016). "A distinctive trait of our study is the use of the recent classification of tumors according to WHO 2021, which excludes IDH-1 mutant patients from GBM and categorizes them as grade 4 astrocytomas." (PMID 36980184, 2023). "Second row (panel β) presents a patient with a WHO III° astrocytoma (MGMT+, IDH1+, LOH1p/19q−) with an ambiguous report concluding that no high-grade recurrence was detected." (PMID 31601829, 2019). "In general, grade II and III astrocytomas are 1p/19q non-deleted and either IDH-1 (isocitrate dehydrogenase-1) wild type or mutant, whereas grade II and III oligodendrogliomas are 1p/19q co-deleted and IDH-1 mutant." (PMID 35690784, 2022). "In sum, 39 IDH1/2-mutant and 1p/19q-codeleted oligodendrogliomas (IDH-mut codel), 39 IDH1/2-mutant astrocytomas (IDH-mut non-codel), 39 IDH1/2-wildtype astrocytomas (IDH-wt), 6 IDH1/2-mutant glioblastomas (GBM IDH-mut), and 39 IDH1/2-wildtype glioblastomas (GBM IDH-wt) were included." (PMID 30203138, 2018).
acute myeloid leukemia (435 papers, 2010 to 2026). Acute myeloid leukemia (AML) is a group of neoplasms arising from precursor cells committed to the myeloid cell-line differentiation. "IDH1/2 mutations are also found in acute myeloid leukemia (AML), with IDH2 mutations being more prevalent, resulting in specific clinical features and a distinct prognosis." (PMID 40075667, 2025). "Mutations in IDH1/2 are frequent in Acute Myeloid Leukemia (AML), defining a molecularly distinct subgroup with therapeutic implications due to the availability of specific inhibitors." (PMID 41226437, 2025). "This approach gained substantial clinical significance, exemplified by the recent regulatory approval of ivosidenib (AG‐120), the first selective mutant IDH1 inhibitor, for the treatment of IDH1‐mutated acute myeloid leukemia." (PMID 40546878, 2025). "Ivosidenib is a potent, orally administered, targeted IDH1 inhibitor originally developed for patients with IDH1-mutated acute myeloid leukemia." (PMID 41008893, 2025). "Ivosidenib is an inhibitor that targets IDH1 and is generally used to treat acute myeloid leukemia (AML) and other types of cancer that carry IDH1 mutations." (PMID 40696413, 2025). "Ivosidenib is a mutant isocitrate dehydrogenase 1 (IDH1) inhibitor that is clinically used to treat patients with relapsed or refractory acute myeloid leukemia (AML) with IDH1 mutation." (PMID 40299557, 2025). "These discoveries have led to the development of specific IDH1/2-mutant inhibitors, such as ivosidenib and enasidenib, which are successful examples of targeting cancer metabolism in patients with IDH1- or IDH2-mutated acute myeloid leukemia." (PMID 39409901, 2024). "Specific gain-of-function mutations in IDH-1 lead to the production of D-2-hydroxyglutarate, a metabolite implicated in the pathogenesis of various cancers, including glioma, acute myeloid leukemia, and iCCA, which is found in 13–25% of cases." (PMID 39057138, 2024). "The present study identified in the IDH1-R132H gene mutation the etiopathogenetic common denominator among Ollier disease, brain glioma, and acute myeloid leukemia coexisting in the same patient." (PMID 39335096, 2024). "TCA cycle enzyme inhibitors, such as the mutant isocitrate dehydrogenase (IDH) inhibitors AG-221 and AG-881, are already in clinical trials for the treatment of IDH2 or IDH1/2-mutated acute myeloid leukemia." (PMID 39609317, 2024). "DNA methyltransferase 3A (DNMT3A) and isocitrate dehydrogenase 1 and 2 (IDH1/2) are genes involved in epigenetic regulation, each mutated in 7–23% of patients with acute myeloid leukemia." (PMID 38791049, 2024). "Our report highlights how IDH1/2 mutations frequently found in acute myeloid leukemia act at the level of hematopoietic precursors in the human system by inducing a block of differentiation." (PMID 39123404, 2024). "Ivosidenib, an inhibitor targeting the mutated IDH-1 enzyme, was initially approved for the treatment of newly diagnosed acute myeloid leukemia." (PMID 39057138, 2024). "Molecularly targeted therapy is now a standard treatment option for patients with acute myeloid leukemia and IDH1/2 or FLT3 mutations." (PMID 36900407, 2023). "On December 1, 2022, the FDA granted approval to olutasidenib, a highly effective inhibitor of isocitrate dehydrogenase-1 (IDH1), to treat relapsed or refractory acute myeloid leukemia (AML) in adults who possess a susceptible IDH1 mutation." (PMID 37661221, 2023). "Treatment with the hypomethylating agents’ showed efficacy in myelodysplastic syndrome and acute myeloid leukemia, a response that appears to correlate with IDH1/2, TET2, and DNMT3A mutations." (PMID 37998740, 2023). "Based on the results of various clinical trials, ivosidenib was approved for acute myeloid leukemia harboring the IDH1 mutation." (PMID 35154988, 2022). "Further works showed that the R132H IDH1 mutation was also a frequent feature of acute myeloid leukemia (AML), encountered in 16% of the studied samples." (PMID 35804976, 2022).
acute myeloid leukemia (continued). "In acute myeloid leukaemia, IDH1 and IDH2 mutations have been associated with the worse outcome, shorter overall survival, and normal karyotype." (PMID 35975235, 2022). "IDH1/2 mutations are a common event in acute myeloid leukemia (AML) and represent a therapeutic target." (PMID 35740677, 2022). "This was rapidly followed by identification of recurrent IDH1/2 mutations in other tumor types, including acute myeloid leukemia (AML)." (PMID 34764443, 2022). "Mutations in IDH1 and IDH2 have frequently been found in acute myeloid leukemia patients, 7% for IDH1 and 14% for IDH2, separately." (PMID 35216362, 2022). "Currently, it is approved for use in patients with IDH1 mutations in acute myeloid leukemia (AML) and CCA." (PMID 35743860, 2022). "IDH1 or 2 mutations also occur in other malignancies, including chondrosarcoma, intrahepatic cholangiocarcinoma, and acute myeloid leukemia (AML)." (PMID 35158978, 2022). "Gain-of-function mutations of isocitrate dehydrogenases 1/2 (IDH1/2) play crucial roles in the development and progression of acute myeloid leukemia (AML), which provide promising therapeutic targets." (PMID 35814406, 2022). "Recently, small-molecule inhibitors of mutant IDH1/2 have been Food and Drug Administration–approved for the treatment of IDH1/2-mutated acute myeloid leukemia." (PMID 34967233, 2022). "Recurrent TET2, DNMT3A, IDH1/2 mutations have been observed in patients with myeloproliferative neoplasms and other hematological malignancies, such as acute myeloid leukemia (AML), chronic myelomonocytic leukemia (CMML), or myelodysplastic syndromes (MDS)." (PMID 33803981, 2021). "Recently, ivosidenib and enasidenib were approved by the FDA to treat acute myeloid leukemia with IDH1 and IDH2 mutations." (PMID 33816227, 2021). "Two genomic sequencing studies published in 2008 and 2009 discovered the high mutation rate of IDH1 in glioblastoma and acute myeloid leukemia (AML), respectively." (PMID 33842477, 2021). "In acute myeloid leukemia (AML) TET2 mutations have been observed to be mutually exclusive with IDH1, IDH2, and WT1 mutations, all of them showing a similar impact on the transcription profile." (PMID 33805247, 2021). "This is an oral IDH1 inhibitor, FDA approved for the treatment of IDH1-mutated acute myeloid leukemia and very recently for advanced or metastatic CCA." (PMID 34638259, 2021). "Mutations of IDH1 were found in 188 acute myeloid leukemia (AML) samples, specifically, R132C, R132H and R132S." (PMID 34200553, 2021). "Meanwhile, IDH1 mutations were also found in the anaplastic thyroid cancer, melanoma, acute myeloid leukemia patients." (PMID 33795525, 2021). "Point mutation of NADP (+)-dependent isocitrate dehydrogenases IDH1(R132H), which occur frequently in glioblastoma, acute myeloid leukemias, etc., showed a strong correlation between tumorigenesis and specific DNA hypermethylation signatures." (PMID 33927716, 2021). "IDH1 is also mutated in acute myeloid leukemia (AML), cholangiocarcinomas, melanomas, chondrosarcomas, fibrosarcoma, and other malignancies." (PMID 33101674, 2020). "In turn, inhibitors of isocitrate dehydrogenase-1 (IDH1) protein are used for the treatment of patients with relapsed or refractory acute myeloid leukemia with a diagnostic mutation in IDH1 gene." (PMID 32111026, 2020). "IDH1 mutations have also been discovered in other cancers, such as colorectal cancer, acute myeloid leukemia, and prostate cancer." (PMID 33262701, 2020). "Experiments on acute myeloid leukemia HL60 line have demonstrated that IDH1 mutation causes an increase in lipid anabolic fluxes and significantly more MUFA and more SFA, albeit not statistically significantly (p = 0.07)." (PMID 32392704, 2020). "Recently, the US Food and Drug Administration approved the use of enasidenib (AG-221) and ivosidenib (AG-120) for the treatment of refractory or relapsed acute myeloid leukemia mutated in IDH2 or IDH1, respectively." (PMID 31010244, 2019).
acute myeloid leukemia (continued). "Early results from trials of ivosidenib (AG-120), a novel inhibitor of mutant IDH1, inIDH1-mutated acute myelogenous leukemia (AML) indicated an overall response rate of 41.6% and a complete remission rate of 21.6%77." (PMID 31069062, 2019). "Recent investigations discovered that IDH1/2 mutations in 20 % of acute myeloid leukemia (AML) population and rarely in breast, lung and prostate cancers." (PMID 35350545, 2019). "Approximately 6–10% of patients with acute myeloid leukemia (AML) have mutations in the isocitrate dehydrogenase 1 (IDH1) gene." (PMID 30881380, 2019). "Isocitrate dehydrogenases 1 and 2 (IDH1/2) are recurrently mutated in acute myeloid leukemia (AML), but their mechanistic role in leukemogenesis is poorly understood." (PMID 31225434, 2017). "In contrast to our results, another team observed that high expression of IDH1 is associated with shorter overall survival in cytogenetically normal acute myeloid leukemia." (PMID 27980696, 2016). "Mutations in IDH1/2 also occur in patients with acute myeloid leukemia (AML), angioimmunoblastic T-cell lymphoma (AITL) and other solid tumors." (PMID 26948489, 2015). "Mutations in the gene encoding isocitrate dehydrogenease 1 (IDH1) occur in various hematopoietic tumors including acute myeloid leukemia (AML), myeloproliferative neoplasms and myelodysplastic syndromes." (PMID 24376688, 2013). "In acute myeloid leukemia IDH1 mutations have been proposed to increase global hypermethylation by blocking the function of the tet oncogene family member 2 function." (PMID 22046342, 2011). "When the clinical data of the predicted fc3 patients in TEMPUS and CPTAC3 were considered, it was found that all cancers harbored IDH1 mutations, a frequent somatic mutation commonly found in acute myeloid leukemia (20%), cholangiocarcinoma (20%), chondrosarcoma (80%), and low-grade gliomas (80%)." (PMID 39941811, 2025). "Finally, a specific mutation involving the IDH1 gene has been documented in the etiopathogenesis of Ollier disease and is present in most sporadic brain gliomas and acute myeloid leukemia." (PMID 39335096, 2024). "Regarding lipid metabolism, Stuani and colleagues studied acute myeloid leukemia cells with a mutation in the enzyme isocitrate dehydrogenase (IDH1), which is common in these resistant cancer cells, and demonstrated the association of the mutation with the impaired lipid anabolism in these cells." (PMID 38611595, 2024). "Ivosidenib, used to treat acute myeloid leukemia, acts on a common cancer‐linked variant of isocitrate dehydrogenase 1 (IDH1 R132H) inhibiting its “gain‐of‐function” activity—the undesired reduction of 2‐oxoglutarate (2OG) to the oncometabolite 2‐hydroxyglutarate (2HG)." (PMID 37607127, 2023). "Olutasidenib has been approved for relapsed or refractory acute myeloid leukemia with mutated IDH1." (PMID 36951997, 2023). "In addition, IDH1/2 mutations are also found in ~20% of cases of acute myeloid leukemia (AML), ~50% of cases of chondrosarcoma, and ~20% of cases of angio-immunoblastic T-cell lymphoma." (PMID 37546420, 2023). "IDH1/2 mutations are common in acute myeloid leukemia (AML) and represent a therapeutic target." (PMID 35740677, 2022). "Notably, AG-221 and AG-881 are in clinical trials for treatment of acute myelogenous leukemia carrying IDH2 or IDH1/2 mutations, respectively." (PMID 35831624, 2022). "Newly diagnosed acute myeloid leukemia (AML) with a susceptible IDH1 mutation." (PMID 36358940, 2022). "DNMT3A and IDH1/2 mutations combinatorically regulate the transcriptome and the epigenome in acute myeloid leukemia; yet the mechanisms of this interplay are unknown." (PMID 36316347, 2022). "Ivosidenib was approved in the United States in 2018 for the treatment of relapsed or refractory acute myeloid leukemia (AML) for patients with the IDH1 mutation, followed by a 2019 FDA-approval for patients susceptible to the IDH1 mutation and upon first diagnosis." (PMID 32751973, 2020).
acute myeloid leukemia (continued). "Besides brain tumors, IDH1 mutations have also been detected in other cancers including acute myeloid leukemia, colorectal cancer, and prostate cancer with low frequencies." (PMID 28498812, 2017). "IDH1 mutations are also associated with acute myeloid leukaemia (AML)." (PMID 29099032, 2017). "TET2 or IDH1/2 mutations are commonly observed in acute myeloid leukemia (AML)." (PMID 28039446, 2017). "Also, genome-wide screening detected IDH1 mutation as a recurrent event in acute myeloid leukemia (AML)." (PMID 26668680, 2016). "Indeed, about 7.7% of acute myeloid leukemia (AML) possessed the IDH1 mutation, but prevalence rates vary between 15 and 33% if IDH2 are also considered." (PMID 26858939, 2016). "IDH1/2 mutations were also reported in acute myeloid leukemias (AML) and cartilaginous tumors." (PMID 24403254, 2013). "Acute myeloid leukemia (AML) harboring IDH1 mutations presents unique metabolic vulnerabilities that remain incompletely addressed by current targeted therapies." (PMID 41938504, 2026). "Mutations in isocitrate dehydrogenase-1 (IDH1) are recurrent in several malignancies and prevalent in acute myeloid leukemia (AML)." (PMID 39406957, 2024). "Ivosidenib (AG-120) is an oral, potent, targeted inhibitor of the mutant IDH1 (mIDH1) enzyme that is approved for the treatment of patients with locally advanced or metastatic cholangiocarcinoma, and subsets of adult patients with acute myeloid leukemia, with a susceptible IDH1 mutation." (PMID 38278871, 2024). "The potential of targeting IDH1 mutations was highlighted, drawing parallels with successes in gliomas and Acute Myeloid Leukemia (AML)." (PMID 38339383, 2024). "IDH1 mutations are also found in leukemias, such as acute myeloid leukemia (AML) and acute lymphoblastic leukemia (ALL)." (PMID 37046844, 2023). "The most common mutations in metabolic enzymes in cancer are somatic mutations in the IDH1/2 genes which are found in >80% of low-grade glioma and ∼20 to ∼30% of acute myeloid leukemia (AML) patients." (PMID 36621625, 2023). "For example, mutations in isocitrate dehydrogenase 1 and 2 (IDH1/2) occur in a subset of acute myeloid leukemia (AML) patients and IDH2 mutant leukemic cells produce elevated levels of the oncometabolite d-2-hydroxyglutarate (D2-HG)." (PMID 37361580, 2023). "In previous studies, mutations in IDH1 were found in association with a variety of malignancies and rare cases, such as low-grade diffuse gliomas, periosteal cartilage tumours, cholangiocarcinoma, acute myeloid leukaemia, and Ollier’s disease and Maffucci’s syndrome." (PMID 37645416, 2023). "Highly specific gain of function mutations in isocitrate dehydrogenase 1 or 2 (IDH1/2) were identified in patients with acute myeloid leukemia (AML) over a decade ago, and have more recently been associated with T-cell leukemias, especially EITP." (PMID 36330381, 2022). "Ivosidenib was initially approved in 2018 by the FDA for the treatment of acute myeloid leukemia (AML) with an IDH-1 mutation but showed great promise in a recent phase III clinical trial in CCA patients." (PMID 35154988, 2022). "Specific cancer cells including gliomas, secondary glioblastomas, and acute myeloid leukemia (AML) overproduce D-2-Hydroxyglutarate (D-2HG) due to point mutations in cytosolic Isocitrate Dehydrogenase 1 (IDH1)." (PMID 36133305, 2022). "Heterozygous IDH1/2 mutations have been predominantly detected in gliomas, with an accumulation of D-2-HG in tumor tissue, and in acute myeloid leukemia (AML), with high serum levels of D-2-HG." (PMID 33916994, 2021). "Two recurrently mutated genes in CHIP and adult acute myeloid leukemia (AML) encode for isocitrate dehydrogenases 1 and 2 (IDH1 and IDH2)." (PMID 32948843, 2021). "Mutations in isocitrate dehydrogenase 1 and 2 (IDH1/2) genes are observed in up to 20% patients with acute myeloid leukemia (AML) and constitute an early clonal event in the evolution of this disease." (PMID 33976256, 2021).